STAT3 (signal transducer and activator of transcription 3)
Diseases named in the same sentence as STAT3 in open-access papers (continued):
Sharing a sentence is not in itself a finding about the gene and the disease.
basal cell carcinoma (10 papers, 2013 to 2025). A carcinoma involving the basal cells. "Loss of Stat3 also produced similar effects in a mouse model of basal cell carcinoma." (PMID 23577258, 2013). "A recent study showed that overexpression of DSG2 induced STAT3 phosphorylation and further increased Gli1 levels in basal cell carcinomas." (PMID 32095325, 2020). "Increased p-Stat3 expression in human SCCs and basal cell carcinomas (BCCs) in comparison to normal skin has been observed in various retrospective studies." (PMID 23577258, 2013). "Similarly, RhoA/ROCK is controlled by the TRPV4 channel and the activation of RhoA/ROCK has been shown to regulate downstream signaling transcription factors including Stat3 and Gli1 in amoeboid cancer cells and basal cell carcinomas, respectively." (PMID 40682198, 2025). "However, the observation that STAT3 is required for the development of basal cell carcinoma driven by augmented SHH signaling suggests that STAT3 will be important in the SHH MB subgroup." (PMID 31683879, 2019). "Expression level of p‐STAT3 (phosphorylation at Tyr705) directly correlates with ligand‐dependent activation of Shh signaling in pulmonary adenocarcinoma, and removal of STAT3 from mouse epidermis dramatically reduced SmoM2‐mediated basal cell carcinoma development." (PMID 34482626, 2022).
chronic obstructive pulmonary disease (10 papers, 2013 to 2024). A chronic and progressive lung disorder characterized by the loss of elasticity of the bronchial tree and the air sacs, destruction of the air sacs wall, thickening of the bronchial wall, and mucous accumulation in the bronchial tree. "The Janus tyrosine kinase/signal transducer and activator of transcription (JAK1/STAT3) pathway plays an important role in the process of acute exacerbation of chronic obstructive pulmonary disease (AECOPD)." (PMID 35571736, 2022). "Rescue of PTPN6 expression or application of a STAT3 inhibitor, effectively protected murine lungs from inflammation and apoptosis, as well as, in part, from the induction of chronic obstructive pulmonary disease (COPD)-like effects." (PMID 29233151, 2017). "In a mouse model of Chronic Obstructive Pulmonary Disease (COPD), IL-9 plays a role in aggravating the lung injury by increasing inflammatory and oxidative stress in a STAT3-dependent manner." (PMID 31035677, 2019). "However, the precise role of STAT3 in the development of airway diseases such as chronic obstructive pulmonary disease (COPD) has not been established." (PMID 24101903, 2013).
Granuloma (10 papers, 2014 to 2025). A compact, organized collection of mature mononuclear phagocytes, which may be but is not necessarily accompanied by accessory features such as necrosis. "Here we show that M. tuberculosis-infected stat3fl/fllysm cre mice, defective for STAT3 in myeloid cells, contained lower bacterial load in lungs and spleens, reduced granuloma extension but higher levels of pulmonary neutrophils." (PMID 29338039, 2018). "The results of this study showed that a chronic infection with Mtb in mice leads to high expression levels of the phosphorylated form of STAT3 (pSTAT3) in the lungs and that pSTAT3 localizes to macrophages and lymphocytes in the granuloma lesions." (PMID 30413750, 2018). "To assess whether dual STAT1/STAT3+ activated macrophages are present in granulomas, and were they are located, we used IHC to visualize the phosphorylated versions of these proteins in NHP granulomas." (PMID 33370784, 2020). "Kidney biopsies showed polymorphic inflammatory cell infiltration (predominantly CD3+ T-cells, most of them demonstrating positive phospho-STAT3 staining) and non-necrotic granuloma in six cases." (PMID 35160055, 2022). "It remains unknown if these mechanisms operate independently or in tandem in granulomas, but results and in vitro studies identifying M1 cells as sources of MMT in biology suggest the STAT1/STAT3 axis is a significant contributor." (PMID 33370784, 2020). "We then highlighted STAT1/STAT3 simulated macrophages that were not exposed to Mtb in images of simulated granulomas to determine where MMT could occur in different granulomas." (PMID 33370784, 2020).
hepatitis B (10 papers, 2014 to 2025). "The ability of the DYRK4-K133 kinase activity to downregulate autophagy via STAT3-FOS axis presents a potential therapeutic target for hepatitis B." (PMID 40303300, 2025). "STAT3 has been shown to play a role in pro- or anti-inflammatory responses in viral liver diseases, such as hepatitis B, which can lead to fibrosis." (PMID 35805137, 2022). "It has also been shown that miR-125b is associated with hepatitis B and has been targeted with genes that include IL6, DDX3X, STAT2, STAT3, SMAD4, CDKN1B, MAP3K1 and so on from our results." (PMID 34988221, 2021). "One interesting finding of our study was that the co-culture of HepG2.215 and dendritic cells activated TLR9/STAT3 signaling and the expression level of TLR9 was positively correlated with HBV DNA in PBMCs from hepatitis B patients." (PMID 30202418, 2018).
hepatoblastoma (10 papers, 2020 to 2026). Hepatoblastoma (HB) is a malignant hepatic tumor and is the most common pediatric liver cancer. "Mechanistically, PVT1 accelerated the cell cycle progression of HB cells by activating STAT3, and inhibiting STAT3 effectively counteracted PVT1's effects on hepatoblastoma cell cycle progression and proliferation." (PMID 38390281, 2024). "Meanwhile, the LNCRNA TUG1 was increased in hepatoblastoma, stimulating the downstream signaling pathway of JAK2/STAT3 and promoting angiogenesis in hepatoblastoma cells." (PMID 36104680, 2022). "In hepatoblastoma cells, STAT3 plays a role in LUCAT1 gene transcription, then, in turn, the lncRNA works as a miR-301b sponge by binding competition and causing the upregulation of STAT3 expression." (PMID 35456025, 2022). "Additionally, within hepatoblastoma, circ-STAT3 increases STAT3 expression through the sponging of miR-29a/b/c/-3p, with this increase contributing to liver malignancy." (PMID 34439334, 2021). "Furthermore, and STAT-3 are representative TFs that have long been associated with Cancer Stem Cells (CSCs), and the absorption of miR-29a/b/c-3p by circ-0043800 in hepatoblastoma cells could induce STAT-3, thus promoting tumor growth." (PMID 39077467, 2024). "STAT3 and RELA/p65 formed a complex in HepG2 hepatoblastoma cells stimulated with IL-1 and IL-6, and NF-κB RELA/p65 homodimers were shown to cooperate with STAT3 in Hep3B cells in response to IL-1." (PMID 39641161, 2024).
hyperlipidemia (10 papers, 2014 to 2024). "A widely used drug, ruxolitinib, is a JAK2/STAT3 inhibitor that causes hyperlipidemia and increases the body mass index." (PMID 36830925, 2023). "The leptin/Janus kinase 2 (JAK2)/signal transducer and activator of transcription 3 (STAT3) pathway is significantly associated with the pathogenesis of hyperlipidemia via alterations in lipid metabolites." (PMID 36539694, 2022). "Together, these data suggest CD146/Gp130 interaction blocks the IL‐6‐induced STAT3 signaling activation and promotes the pro‐inflammatory polarization of ATMs under hyperlipidemia conditions." (PMID 35258174, 2022). "COE activates the leptin/JAK2/STAT3 pathway, leading to an improvement in liver function and lipid metabolism and ultimately alleviating hyperlipidemia in rats." (PMID 36539694, 2022). "Collectively, the protective role of COE in hyperlipidemia is carried out via STAT3-involved oxidative stress and lipid metabolism." (PMID 36539694, 2022). "That is, SOCS3, as a classic negative regulator of JAK2/STAT3, was up-regulated with the progression of inflammation aggravated by hyperlipidemia." (PMID 32169038, 2020). "For instance, rhizoma polygonati polysaccharide from Polygonatum sibiricum and resveratrol from Reynoutria japonica improved serum lipids in hyperlipidemia-mediated AS mice and attenuated IL-6-p-STAT3 signaling." (PMID 30713570, 2019). "Leptin may contribute to hyperlipidemia through the OB-R-mediated activation of the JAK2/STAT3 pathway, which affects lipid metabolism and fat deposition in hepatic tissue." (PMID 36539694, 2022). "Thus, we propose that the leptin/JAK2/STAT3 pathway may be the regulatory target of COE in hyperlipidemia treatment." (PMID 36539694, 2022). "Thus, quercetin may mediate the role of COE in the leptin/OB-Rb/JAK2/STAT3 pathway in a rat model of hyperlipidemia." (PMID 36539694, 2022). "Under hyperlipidemia conditions, CD146 interacts with Gp130 to inhibit ACM (mainly IL‐6)‐induced STAT3 activation." (PMID 35258174, 2022). "leaf (COE) in hyperlipidemia via the leptin/Janus kinase 2 (JAK2)/signal transducer and activator of transcription 3 (STAT3) pathway." (PMID 36539694, 2022).
interstitial lung disease (10 papers, 2019 to 2025). A diverse group of lung diseases that affect the lung parenchyma. "In this study, we describe a case of IEI with a predominant interstitial lung disease (ILD) phenotype and arthritis due to STAT3 GOF mutation." (PMID 40703313, 2025). "Enhanced IL-6 signaling has been shown to contribute to interstitial lung disease (ILD) pathogenesis, through the IL-6/STAT3/IL-17A signaling pathway." (PMID 36543914, 2022).
intestinal tumor (10 papers, 2016 to 2021). "In contrast, IEC-specific STAT3-deficient mice exhibit decreased intestinal tumors." (PMID 33996591, 2021). "In summary, MLKL exhibits a suppressive effect in the progression of intestinal tumors by regulating the IL-6/JAK2/STAT3 axis." (PMID 33767595, 2021). "To evaluate the status of STAT3 in intestinal epithelial cells and tumors from Apcmin/+Ripk3-/- mice, we analyzed protein expression in intestinal tumors and colon crypt cells." (PMID 33996591, 2021). "To further confirm the role of MLKL on STAT3 activation during intestinal tumorigenesis, we examined STAT3 activation in 16-week-old Apcmin/+Mlkl-/- and Apcmin/+ intestinal tumors." (PMID 33767595, 2021). "The production of inflammatory cytokines and the phosphorylation of STAT3 were both inhibited in intestinal tumor cells." (PMID 30498394, 2018). "Other groups have shown that the gp130-Jak-STAT3 signaling pathway promotes intestinal tumor growth and regeneration, as does Wnt signaling." (PMID 27259262, 2016). "Thus, our results reveal that RIPK3 is a tumor suppressor in spontaneous intestinal tumorigenesis, and implicate targeting the IL-6/STAT3 signaling axis as a potential therapeutic strategy for intestinal tumor patients with reduced RIPK3." (PMID 33996591, 2021). "Constitutively activated STAT3 in mice is resistant to intestinal tumor development." (PMID 33996591, 2021). "Next, we sought to explore whether the IL-6/STAT3 axis contributed to the increase in intestinal tumors in Apcmin/+Mlkl-/-mice." (PMID 33767595, 2021). "Our results also highlight that interfering with IL-6/STAT3 axis could be a better therapeutic option for intestinal tumor patients with low MLKL expression." (PMID 33767595, 2021).
thymoma (10 papers, 2013 to 2025). A neoplasm arising from the epithelial cells of the thymus. "Our results suggest that MAIT cells are both reduced and functional deficient in STAT3 deficiency and thymoma patients with IL-12/23 autoantibodies." (PMID 27167980, 2016). "The most frequently mutated genes within each subtype were as follows: PCLO (27%), POT1 (27%), and STAT3 (27%) in idiopathic PRCA; STAT3 (20%), DNMT3A (10%), and CUX1 (10%) in thymoma-associated PRCA; and STAT3 (54%) and TET2 (12%) in LGLL-associated PRCA." (PMID 40202536, 2025). "Concerning the genetic background of PRCA, somatic STAT3 mutations, particularly frequent in LGLL, have been detected in patients with various types of PRCA, including idiopathic, LGLL-associated and thymoma-associated PRCA." (PMID 40202536, 2025). "Our research screened out the core target genes AKT1, MMP9, STAT3, SRC, and EGFR of thymoma-associated M, and carried out molecular docking verification." (PMID 37498332, 2024). "Inducible expression of MS3-6-VHL fusions in NPM-ALK expressing mouse thymoma cells resulted in the degradation of endogenous STAT3 protein." (PMID 32807795, 2020). "EL4 mouse thymoma cells were transiently transfected with a luciferase reporter construct containing this sequence and a plasmid coding for an active form of STAT3 (STAT3C)." (PMID 23923047, 2013). "Moreover, in line with previous studies on mouse thymoma cells exposed to tributyltin oxide, another EDC, we observed positive correlations between some POPs and increased expression of the RRM2 gene, which has been reported to promote EMT through the STAT3 cascade." (PMID 38674005, 2024).
thyroid (10 papers, 2010 to 2024). "We found that exogenous expression of STAT3 abrogated the effect of LDR on thyroid carcinogenesis as shown by soft agar colony formation and sphere formation assays in BCPAP cells." (PMID 30760304, 2019). "Similarly, multiple signaling pathways, such as IGF-1, STAT3, and Shh, play a role in regulating thyroid CSC growth." (PMID 26973599, 2016). "Of course, from our small sample size comprising patients with chronic, long-lasting thyroiditis, we cannot exclude the possibility that thyroidal expression of STAT3 may be more prominent in earlier stages of the disease." (PMID 22527947, 2012).
thyroid tumor (10 papers, 2014 to 2024). A benign or malignant neoplasm affecting the thyroid gland. "We found that S3I-201 effectively inhibits HFD-induced aberrant activation of STAT3 and its downstream targets to markedly inhibit thyroid tumor growth and prolong survival." (PMID 27145454, 2016). "Metform in lowered p-STAT3 (Y705) protein levels in thyroid tumors of HFD-ThrbPV/PVPten+/−mice (compare lanes 10-12 to lanes 4-6) without changing the total STAT3 protein levels." (PMID 27145454, 2016). "We further carried out immunohistochemical analysis to determine the protein abundance of p-STAT3 (Y705) in thyroid tumor cells in ThrbPV/PVPten+/−mice." (PMID 27145454, 2016). "To explore the mechanisms underlying the effect of gravity on thyroid protein fraction, we examined proteins relevant for the thyroid function; Caveolin-1 which is a critical protein to caveolae and STAT3 which is a suppressor of thyroid tumor growth." (PMID 24866829, 2014). "Moreover, FAK expression is critical for thyroid tumor tumorigenesis and growth 35, and activation of STAT3 enhances tumor cell proliferation and prevents apoptosis in most cancers." (PMID 38773979, 2024).
Wiskott-Aldrich syndrome (10 papers, 2016 to 2025). Wiskott-Aldrich syndrome (WAS) is a primary immunodeficiency disease characterized by microthrombocytopenia, eczema, infections and an increased risk for autoimmune manifestations and malignancies. "Sixty-four patients had a Del 22q11.2 defect (DiGeorge syndrome), 63 had an ataxia telangiectasia mutated gene (ATM) (A-T), 36 had a STAT3 mutation (Hyper IgE syndromes), 24 had a WASP mutation [Wiskott-Aldrich syndrome (WAS)]." (PMID 31379802, 2019). "SCID, CIDs, DiGeorge syndrome, Wiskott-Aldrich syndrome, Ataxia telangiectasia, Dyskeratosis congenita, ORAI-1 deficiency, CGD, X-linked Agammaglobulinemia, ALPS, STAT1 gain of function, CTLA-4 deficiency, GATA-2 deficiency, TRAPS, FMF, NEMO, TIM3, DOCK8, STAT2, STAT3, PIK3CD." (PMID 41049857, 2025).
acromegaly (9 papers, 2017 to 2025). Acromegaly is an acquired disorder related to excessive production of growth hormone (GH) and characterized by progressive somatic disfigurement (mainly involving the face and extremities) and systemic manifestations. "Next, we tried to find out the associations between STAT3 gene promoter methylation and patient clinical characteristics: gender, age at the time of operation, relapse, PA function, invasiveness and diagnoses of Cushing syndrome, acromegaly or prolactinoma." (PMID 28709401, 2017). "Signal transducer and activator of transcription 3 (STAT3) is located on 17q21.2, and its enhancement increases GH transcription, supporting the development of somatotroph adenomas." (PMID 40299639, 2025). "Differences between transcriptomic groups were also observed in expression levels of proliferation-related genes CCND1, CDKN1B, and MKI67 and genes involved in cell signaling TGFB1 and STAT3 that all have a reported role in acromegaly patients’ outcome." (PMID 36497102, 2022). "In primary human somatotroph adenoma-derived cell cultures, the specific inhibitor S3I-201 can inhibit STAT3 expression, thus decreasing GH transcription and reducing GH secretion." (PMID 33574795, 2020). "Its expression is enhanced in somatotroph adenomas, leading to GH hypersecretion, which in turn promotes STAT3 expression." (PMID 33574795, 2020). "The FGFR4-R388 allele, which is associated with larger pituitary tumor size in patients with acromegaly, modulates STAT3 phosphorylation status, resulting in altered hormone regulation and enhanced cell proliferation in pituitary cells." (PMID 27966451, 2017). "They found that STAT3 expression was significantly enhanced in somatotroph adenomas (67% ± 5%) as compared with non-secreting pituitary tumor expression (unpaired t test, P < 0.001)." (PMID 28709401, 2017).
autoimmune lymphoproliferative syndrome (9 papers, 2016 to 2024). Autoimmune lymphoproliferative syndrome (ALPS) is a rare, inherited disorder characterized by non-malignant lymphoproliferation, multilineage cytopenias, and a lifelong increased risk of Hodgkin's and non-Hodgkin's lymphoma. "The severe lymphoproliferation observed in patients with STAT3 GOF has been described as a mimic of Autoimmune Lymphoproliferative Syndrome (ALPS)." (PMID 36843887, 2022). "Key IEI-associated alterations causative of STAT3 GOF disease, IKAROS haploinsufficiency, activated PI3Kδ syndrome (APDS), Kabuki syndrome and autoimmune lymphoproliferative syndrome (ALPS) were identified." (PMID 35058929, 2021).
cerebral infarction (9 papers, 2016 to 2025). An ischemic condition of the brain, producing a persistent focal neurological deficit in the area of distribution of the cerebral arteries. "STAT3 plays a critical role in neuroprotection through the neuroprotective gene bc1-2, and the inhibition of STAT3 can result in the increase of cerebral infarction." (PMID 38022526, 2023). "The inhibition of IL-6 decreases STAT3 phosphorylation, which leads to the exacerbation of cerebral infarction." (PMID 38022526, 2023). "Indeed, previous studies have documented that STAT3 activation occurs in neurons, astrocytes and microglia/macrophages after focal cerebral infarction and may provide beneficial effects through a variety of mechanisms." (PMID 31849581, 2019). "Our study provides new evidence that i-HPK1 suppresses neutrophil hyperactivation by blocking NF-κB/STAT3/p38-MAPK and GSDMD pathways and neutrophil trafficking into the brain and lungs, ultimately alleviating cerebral infarction and pulmonary injury following AIS." (PMID 40169896, 2025). "An animal study shows that Xuesaitong (Panax notoginseng-based CPM) reduces brain infarct volume and alleviates neurological impairment 14 days after middle cerebral artery occlusion (MCAO), possibly by regulating microglial phenotypes via downregulation of the STAT3 signaling pathway." (PMID 38796623, 2024). "Similarly, we observed that pharmacological Stat3 inhibition in combination with IFNβ treatment also did not yield improvement to brain infarction volume." (PMID 27683877, 2016).